TNIK (TRAF2 and NCK interacting kinase)
Diseases named in the same sentence as TNIK in open-access papers (continued):
Sharing a sentence is not in itself a finding about the gene and the disease.
cancer (34 papers, 2012 to 2026). A tumor composed of atypical neoplastic, often pleomorphic cells that invade other tissues. "Traf2- and Nck-interacting kinase (TNIK) has been reported as a serine/threonine kinase associated with tumor cell proliferation or unfavorable cancer behavior." (PMID 38226156, 2024). "TNIK is also involved in other cancer-associated processes through alternative targets including AKT signaling, autophagy and the epithelial to mesenchymal transition, and modulation of these processes would also have to be considered when targeting the kinase." (PMID 40061138, 2025). "TNIK is essential for the transactivation of Wnt signal target genes, and its expression is associated with poor prognosis in patients with hepatocellular, colorectal, and pancreatic cancers." (PMID 33400690, 2021). "TNIK is one of the germinal center kinase family members involved in cytoskeleton organization and neural dendrite extension, and is reported to be associated with the progression of several human cancers." (PMID 26499327, 2015). "Thus, our data implicate TNIK in LMP1- and CD40-induced cancer and indicate the potential of TNIK as a future target for therapy of EBV and CD40-associated malignancies." (PMID 22904686, 2012). "Although the role of TNIK in certain cancers has been extensively documented, its role in CRPC remains less understood." (PMID 38226156, 2024). "Traf2 and Nck-interacting kinase (TNIK) is known for its regulatory role in various processes within cancer cells." (PMID 38264262, 2023). "Several studies have explored the potential of pharmacological TNIK inhibition to hinder cancer growth." (PMID 38264262, 2023). "In comparison to the anti-cancer drug fluorouracil, Chr and EM both demonstrated better binding scores against the protein targets caspase-3, apoptosis regulator Bcl-2, TNIK, and CDK2." (PMID 36355520, 2022). "According to our docking data, EM and Chr were the most attractive for cancer targeting proteins TNIK and CDK2, followed by caspase-3." (PMID 36355520, 2022). "Pharmacological TNIK inhibition would be potentially applicable to the management of various EMT-associated disorders; not only metastasis, but also cancer stemness and chemotherapy resistance." (PMID 33244122, 2021). "In the last decade, Traf2- and Nck-interacting kinase (TNIK) has been reported as a first-in-class cancer target molecule." (PMID 32810161, 2020). "Traf2- and Nck-interacting kinase (TNIK) has recently been considered as an anti-proliferative target molecule to regulate the Wnt signaling pathway in several types of cancer cells." (PMID 32810161, 2020). "Mebendazole, a familiar drug in anti-helminthic ailments, was found to possess anti-cancer properties in pre-clinical models of several cancers, and was shown to inhibit the kinase activity of TNIK." (PMID 29914080, 2018). "In many studies, the expression of TNIK has been shown to be involved in the survival of human cancer cells, including colorectal, gastric, liver, and hematological cancer." (PMID 28467797, 2017). "Through these our recent reports, we confirmed that TNIK can be a potential target for inducing apoptosis activity of KY-05009 and dovitinib in cancer cells." (PMID 28467797, 2017). "In the last 10 years, TNIK has been reported as a novel therapeutic target in several types of cancers." (PMID 28467797, 2017). "A few reports have demonstrated the expression of TNIK and cancer cell proliferation in several types of cancer, but the relevance of TNIK to hematological malignancies, especially MM, has not been sufficiently described." (PMID 28467797, 2017). "Traf2- and Nck-interacting kinase (TNIK) has recently been considered as a first-in-class anti-cancer target molecule to regulate Wnt signaling pathway, but pharmacologic inhibition of its EMT activity has not yet been studied." (PMID 25337707, 2014). "Recent reports have proposed the Traf2- and Nck-interacting kinase (TNIK) as a first-in-class anti-cancer target molecule." (PMID 25337707, 2014).
cancer (continued). "In order to validate TNIK as a druggable, anti-cancer target molecule, it is essential to verify the pharmacologic relevance of targeting TNIK." (PMID 25337707, 2014). "Continuing efforts to identify and validate potential therapeutic targets associated with EMT, such as TNIK, provide new and improved therapies for treating and/or preventing EMT-based disorders, such as cancer metastasis and fibrosis." (PMID 25337707, 2014). "While TNIK has been associated with poor prognosis in PDAC, evidence suggests that oncogenic mechanisms may differ according to cancer type." (PMID 40492125, 2025). "TNIK has garnered attention as a key regulator within the β-catenin and T-cell factor-4 (TCF-4) transcriptional complex which is a critical signaling pathway implicated in cancer development and progression." (PMID 39011472, 2024). "In BET bromodomain inhibitor JQ1‐resistance HCT116 cells, which showed high resistance to various anti‐cancer drugs, including cisplatin, TNIK (TRAF2 and NCK‐interacting protein kinase) was a regulator of Wnt/β‐catenin signaling and transactivate cyclin D1 (CCND1) and cyclin E1 (CCNE1)." (PMID 36408691, 2023). "Moreover, MBZ can modulate various cancer-associated pathways, including MAPK14, MEK-ERK, C-MYC, USP5/c-Maf, TNIK, XIAP, ELK/SRF, NFKB, MYC/MAX, E2F/DP1, TGF/SMAD, AP1, and STAT1/2, dependent on the specific cancer model." (PMID 36674870, 2023). "Consequently, most research efforts have been concentrated on understanding the involvement of TNIK in cancer growth, leading to the development and testing of small-molecule TNIK inhibitors like NCB-0846 for their anti-tumor effects." (PMID 38264262, 2023). "Overall, our findings provide insight into the immunogenic nature of TNIK inhibition in Wnt-addicted cancers, which can motivate future clinical trials, especially with FDA-approved TNIKi, such as mebendazole, in combination with checkpoint inhibitors and/or other immunotherapies." (PMID 35675910, 2022). "Notably, we previously reported the potential of TNIK as an anti-cancer target molecule on the TGF-β induced EMT process, migration, and invasion of human lung adenocarcinoma cells." (PMID 32810161, 2020). "TNIK has also been reportedas a novel therapeutic target in several types of cancers studies, the expression of TNIK has been proved to be involved in the survival of human cancer cells which includes colorectal,gastric, liver, and hematological cancer." (PMID 32831519, 2020). "These previous studies indicate that TNIK-mediated activation of Wnt signaling could be a therapeutic target in the development of anti-cancer agents." (PMID 28467797, 2017). "Therefore, RAP2 might regulate cancer cell proliferation and invasion via activating the TNIK/Wnt signalling cascade." (PMID 35538031, 2022). "In addition, overexpression of nuclear TNIK is related to the prognosis of cancer." (PMID 28467797, 2017). "Thus, our results suggest that TNIK could be an anti-cancer target for the investigation of treating MM by inhibiting Wnt signaling-mediated MM cell proliferation." (PMID 28467797, 2017). "We found less literature on anthraquinone analogue binding mechanisms and interaction energy with caspase-3, apoptosis regulator Bcl-2, TNIK, and CDK2, important cancer-related protein targets." (PMID 36355520, 2022). "We prioritized models based on relative chemotherapy resistance of the original patient’s cancer from which the PDX model was derived, as well as levels of expression of 108600 targets (CK2, DYRK, and TNIK kinases)." (PMID 34344863, 2021). "Through the interaction with TCF4 and β-catenin, TNIK phosphorylates TCF4 at serine 154, and mediates the activation of Wnt target genes that are involved in cancer cell growth." (PMID 25337707, 2014). "Here, using 5-(4-methylbenzamido)-2-(phenylamino)thiazole-4-carboxamide (KY-05009) with TNIK-inhibitory activity, its efficacy to inhibit EMT in cancer cells was validated." (PMID 25337707, 2014).
cancer (continued). "For ITGA2, SLC1A5, TIAM1, TNIK, and ABTB2, several studies showed that their high expression played a significant role in promoting tumor cell growth and inhibiting cell apoptosis from chemotherapy in different kinds of cancers." (PMID 35267472, 2022). "As sunitinib also has been shown to inhibit TNIK kinase activity, and to address the relevance between TNIK inhibition and TGF-β1-induced EMT, we evaluated the effect of sunitinib as an anti-cancer agent inhibiting TNIK kinase activity and the EMT in NSCLC cells." (PMID 32810161, 2020). "In the present study, we conducted comprehensive modeling studies of TNIK inhibitors and developed CoMFA/CoMSIA, kNN, and CoMSIA-SIMCA models, which were then rationally applied to screen and identify an approved drug, mebendazole, as a potent TINIK inhibitor for cancer therapy." (PMID 27650168, 2016). "TNIK protein was observed in the cytoplasm of cancer cells, but not in normal epithelial cells." (PMID 26499327, 2015).
tumor (26 papers, 2010 to 2025). "In the present study, high expression of TNIK was significantly associated with tumor depth (T4), lymphatic invasion, and venous invasion." (PMID 26499327, 2015). "In recent years, several small molecule compounds targeting TNIK have been investigated for their anti-tumor effects." (PMID 39011472, 2024). "To validate the microarray results, we performed qPCR analysis on xenograft tumor samples from CR-LNCaP (4 castrations) and HS-LNCaP (4 uncastrations), confirming higher mRNA expression of TNIK in CR-LNCaP compared with HS-LNCaP." (PMID 38226156, 2024). "By selectively inhibiting TNIK, these agents exert their effects on downstream signaling pathways, disrupting aberrant Wnt signaling and impeding tumor growth and progression." (PMID 39011472, 2024). "The use of TNIK inhibitors achieved complete tumor control in 50% of mice when combined with immune checkpoint inhibitor targeting PD-1." (PMID 35675910, 2022). "The goal of the current study was to temporally profile the tumor microenvironment in murine CRC undergoing TNIK inhibition." (PMID 35675910, 2022). "Our results indicate that both compounds robustly inhibit TNIK in tumor cells and lead to CD8+ T cell infiltration." (PMID 35675910, 2022). "Traf2 and Nck interacting serine protein kinase (TNIK) has been considered as an important activator of Wnt signaling pathway to promote tumor progression and invasion." (PMID 35095493, 2021). "In summary, we have identified an active TNIK state in OS and demonstrated that TNIK inhibition suppressed tumor growth, abrogated OS stemness, and induced adipogenic conversion in vitro and in vivo." (PMID 33400690, 2021). "We found that TNIK staining tended to be stronger at the invasive tumor front than at the tumor marginal site." (PMID 26499327, 2015). "TNIK phosphorylates TCF4,and a kinase-dead mutant of TNIK abrogated β-catenin/TCF-driven transactivation.siRNA-mediated inhibition of TNIK had an anti-proliferative effect invitro, and inhibited tumor growth in an HCT116 xenograft model." (PMID 21317452, 2010). "The efficacy of the small molecule TNIK inhibitor NCB-0846 on tumor cells has been confirmed." (PMID 38226156, 2024). "The NCB-0846 inhibitor was effective in interfering with TNIK activity tumour growth." (PMID 33080952, 2020). "GRN, CD5L, ENO1, CHL1, CRISP3, VASN, and TNIK promote the invasive ability of tumor cells." (PMID 32953262, 2020). "We conclude that TNIK is required for the tumour-initiating function of colorectal CSCs." (PMID 27562646, 2016). "Therefore, we focused on TNIK expression at the invasive tumor front, and used the staining scores at the invasive tumor front in further analysis." (PMID 26499327, 2015). "Our results supported the idea that high expression of TNIK at the invasive tumor front might play an important role in progression and distant metastasis of CRC." (PMID 26499327, 2015). "By inhibiting the TNIK/EGFR axis, NCB-0846 showed inhibitory effects on CRPC tumor cells both in vivo and in vitro and blocked EMT of tumor cells as well as bone metastasis." (PMID 38226156, 2024). "As a practical TNIK inhibitor, NCB-0846 can bind to the ATP active pocket of TNIK, making it unable to phosphorylate TCF4, thereby exerting a tumor suppressive effect." (PMID 36287174, 2022). "By downregulating Wnt-driven immunosuppression—which is known to exclude T-cells from the tumor microenvironment—TNIK inhibitors may sensitize “cold” TNBC tumors to anti-PD-1 therapies, positioning TNIK as a dual-purpose target for eradicating stemness and enhancing immunity." (PMID 41516322, 2025). "Most of these OS tissue samples showed TNIK protein expression in the nuclei with varying degrees of positivity (grade 0 [no nuclear staining] to grade 5 [>75% of viable tumor cells])." (PMID 33400690, 2021).
tumor (continued). "Furthermore, in SW620, administration of axitinib led to a significant tumor growth inhibition, which might be attributed to its relatively high expression of axitinib targets FGFR1 and TNIK." (PMID 31783534, 2019). "In tumor biopsies from non-responders, GPR110 and TNIK were significantly upregulated, while WDR4 and BRCA1 were significantly downregulated, as compared to those of responders (p < 0.05)." (PMID 34572869, 2021).
infection (4 papers, 2014 to 2024). The state of being infected such as from the introduction of a foreign agent such as serum, vaccine, antigenic substance or organism. "We documented a reduced expression of Wnt target genes in TNIK KO p14 T cells early after activation in vitro and 48 h after infection in vivo." (PMID 32242021, 2020). "Moreover, numerous Ser/Thr kinases (STKs) were either increased (e.g., GRK2, ROCK2, ROCK1, PAK1) or decreased (e.g., BMP2K, TNIK, MYLK, and NRBP1) in expression in the patient samples, suggesting a widespread change in the kinome caused by pathogen infection." (PMID 38389037, 2024). "Next, we investigated the impact of TNIK depletion on the response of ECs to Ad-WT infection." (PMID 38264262, 2023). "The protein network supports the idea that depleting TNIK hampers IFN signaling and the antiviral response while promoting viral replication and infection." (PMID 38264262, 2023). "The figure underscores the inhibitory effect of TNIK depletion on IFN signaling and the antiviral response while enhancing viral replication and infection." (PMID 38264262, 2023). "Purified splenic Cd45.1+Tnik−/− (KO) and Cd45.2+ TNIK competent (WT) p14 T cells were adoptively co-transferred (AdCoTf) at a ratio of 1:1 into Cd45.1+.2+-recipient mice 1 day prior to infection with 104 pfu LCMV." (PMID 32242021, 2020).
psychiatric disorder (3 papers, 2024 to 2025). A disorder characterized by behavioral and/or psychological abnormalities, often accompanied by physical symptoms. "Genome-wide association studies and functional analyses have linked TNIK to psychiatric disorders, with TNIK knockout mice exhibiting hyper-locomotor behavior reversible by glycogen synthase kinase 3β (GSK3β) inhibitors." (PMID 40672381, 2025). "One of these proteins, the Traf and Nck interacting kinase (TNIK), is a postsynaptic density (PSD) signaling hub, with many variants reported in neurodevelopmental disorder (NDD) and psychiatric disease." (PMID 38638602, 2024).
brain disorder (1 paper, 2024). A disease affecting the brain or part of the brain. "However, TNIK interactomes are enriched in risk factors for complex brain disorders." (PMID 38638602, 2024).
neurological disorders (1 paper, 2018). "So, we propose that the Sema/Plexin/Rap2/TNIK signaling pathway plays a critical role to precisely define synaptic connections and its disruption may induce serious neurological disorders." (PMID 30063210, 2018).
TNIK also shares sentences with these, for which no sentence is quoted: thyroid cancer (4 papers); osteosarcoma (3); hematological cancer (2); acute myeloid leukemia (1); allergic respiratory disease (1); anemia (1); artery disease (1); autism spectrum disorder (1); bipolar disorder (1); cardiovascular diseases (1); chronic kidney disease (1); depression (1); developmental delay (1); endometrial cancer (1); endothelial dysfunction (1); epileptic seizures (1); hematological malignancies (1); hepatocellular carcinoma (1); Hyperinsulinemia (1); Hypertension (1); Insulin resistance (1); lupus erythematosus (1); melanoma (1); mesothelioma (1); neurodegenerative disease (1); neurodevelopmental disorder (1); ovarian carcinoma (1); renal clear cell carcinoma (1); rheumatoid arthritis (1); squamous cell carcinoma (1).
A further 3 diseases each share a sentence with TNIK in 1 paper.